CRP (C-reactive protein)
Diseases named in the same sentence as CRP in open-access papers (continued):
Sharing a sentence is not in itself a finding about the gene and the disease.
Hepatic steatosis (continued). "The reduced hepatic steatosis in obese rats is accompanied by decreased systemic inflammation [i.e., serum C-reactive protein (CRP)]." (PMID 38075211, 2023). "Consistent with the improvement in liver steatosis, plasma lipids and lipoprotein levels, a statistically significant reduction in the inflammatory marker us-CRP was obtained." (PMID 36769628, 2023). "The results showed that higher BMI and CRP values are related to liver steatosis (BMI—OR 1.459; P = .001; 95% CI 1.177–1.808; CRP—OR 1.387; P = .026; 95% CI 1.039–1.850)." (PMID 34241914, 2022). "Previous studies have found that the degree of hepatic steatosis and inflammation correlated with systemic levels of inflammatory biomarkers including C-reactive protein (CRP)." (PMID 35857770, 2022). "Results showed a significant decrease in total cholesterol (p = 0.016), triglyceride (p = 0.049), hepatic steatosis (p = 0.041), and C-reactive protein levels (p = 0.029) versus placebo, probably due to an inhibition of the NF-kB pathway." (PMID 35565680, 2022). "The multivariate logistic regression showed that for one unit enlargement in the DICA score, total cholesterol, and CRP, the chance for the presence of hepatic steatosis enlarged 1.29, 1.40, and 1.01 times, respectively." (PMID 35056346, 2021). "Regression models were used to assess the relationships between log-hs-CRP (dependent variable) and post-surgery fatty liver disease and success rate (independent variables)." (PMID 33919641, 2021). "Fatty liver disease, liver injury, total bilirubin, ALT, AST, LDH, CRP, GGT, platelet count, and albumin level were associated with more severe disease course." (PMID 33282888, 2020). "Although the liver is known to be a major source of CRP, it is the accumulation of fat both in the adipose tissue and in liver steatosis that leads to increased CRP levels among obese patients." (PMID 29887885, 2018). "Fatty liver in early CT scan can predict the delayed elevation of serum CRP; thus, fatty liver can be a prognostic marker easily determined at initial diagnosis." (PMID 28536603, 2017). "Higher serum CRP levels were consistently found in fatty liver patients compared to controls in previous studies." (PMID 28536603, 2017). "Univariate logistic regression analysis revealed that MetS scores 2 and ≥3, endotoxin, hs-CRP, and WBC count were positively associated with the 1H-MRS-measured degree of fatty liver." (PMID 27079922, 2016). "A recent study evaluated the prevalence of elevated plasma high sensitivity CRP (hs-CRP) concentrations and hepatic steatosis in MHO, MHNW, and in metabolically unhealthy normal-weight (MUNW) individuals." (PMID 27258304, 2016). "Our study showed a significant difference in CRP levels between patients with severe fatty liver and controls." (PMID 23924883, 2013). "This study revealed that CRP is a novel early biomarker of alcohol-induced fatty liver, and that CRP and Hp were both particularly decreased with liver fibrosis." (PMID 21806828, 2011). "Moreover, CRP, a marker of systemic inflammation, is generally elevated in conditions like chronic low-grade inflammation, fatty liver, and liver damage." (PMID 40883838, 2025). "They found a positive correlation between the severity of liver steatosis and hs-CRP." (PMID 39842820, 2025). "We measured changes in hepatic steatosis, non-invasive fibrosis scores, inflammatory markers (including interleukin-6, tumor necrosis factor-alpha, and highly sensitive C-reactive protein), liver enzymes, and lipid profiles at baseline and at the end of the 24 weeks." (PMID 41011150, 2025). "Likewise in prospective non randomized intervention trial following a MD significantly decreased body fat along with BMI and hepatic steatosis and inflammation markers such as hs-CRP levels and OxLDL." (PMID 41010458, 2025). "Additionally, elevated IL-6 and CRP levels are known to suppress hepatic glycolysis and contribute to fatty liver disease progression." (PMID 40507158, 2025).
Hepatic steatosis (continued). "As an important marker of the inflammatory response, the CRP level in patients with fatty liver may increase, reflecting the inflammatory state of the liver." (PMID 41480537, 2025). "In conclusion, systemic inflammation levels are significantly associated with hepatic steatosis and NAFLD risk, with CRP having the strongest correlation and composite systemic inflammatory indicators being more strongly correlated than any individual blood cell count variable." (PMID 38979415, 2024). "The data suggests that KKT may reduce the production of CRP from the liver and suppress the systemic inflammation and development of fatty liver disease." (PMID 38742193, 2024). "In non-alcoholic fatty liver patients, due to functional resistance training, EF (p-value = 0.003) and FS (p-value = 0.03) significantly increased, and C-reactive protein (Hs-CRP) (p-value = 0.001), steatosis (p-value = 0.04), and stiffness (p-value = 0.01) decreased." (PMID 37726373, 2023). "Additionally, the evaluated characteristics of metabolic dysregulation (fasting glucose, systolic blood pressure, triglycerides, total cholesterol, and CRP) were more prominent in colonic diverticulosis patients in whom hepatic steatosis was detected." (PMID 35056346, 2021). "In patients with colonic diverticulosis and concomitant hepatic steatosis, the fasting glucose, total cholesterol, triglycerides, CRP levels, systolic blood pressure value, as well as AST, ALT, ALP and GGT levels were all more prominent compared to those without hepatic steatosis." (PMID 35056346, 2021). "Based on the anti‐inflammatory and antihypertensive properties of garlic, the current study was designed to evaluate the garlic powder effects on blood pressure and high‐sensitivity C‐reactive protein (hs‐CRP) among Nonalcoholic Fatty Liver Disease patients (NAFLD)." (PMID 34262716, 2021). "Interestingly, PAI-1 and CRP showed increasing levels when compared between the different levels of hepatic steatosis." (PMID 32151020, 2020). "It is notable that ICAM-1 and CRP were also associated with fatty liver independent of VAT among HIV-uninfected men." (PMID 28929125, 2017). "Our first major finding was that higher levels of proinflammatory biomarkers (ICAM-1, CRP, IL-6, and TNFαR2) and lower levels of the anti-inflammatory adiponectin were associated with fatty liver among HIV-uninfected men independent of VAT." (PMID 28929125, 2017). "The biomarkers that we found to be independently associated with fatty liver, lower adiponectin, and higher ICAM-1, CRP, IL-6, and TNFαR2 are also predictive of cardiovascular events, suggesting a potential explanation for a direct link between fatty liver and cardiovascular events." (PMID 28929125, 2017). "Hepatic steatosis may exaggerate the synthesis of high sensitivity CRP or other mediators by the liver, thereby increasing its systemic levels." (PMID 27547235, 2016). "In conclusion, we present CRP as a surveillance marker of alcohol-induced fatty liver in a rodent model, which may help diagnose early alcohol-induced pathophysiological alterations in clinical practice." (PMID 21806828, 2011). "Beside, three patients with focal fatty liver disease had normal serum CRP levels." (PMID 19222849, 2009). "And the associations of CRP, IL-1β, and IL-6 with hepatic steatosis were not significant." (PMID 35603224, 2022). "Lean IBD patients exhibited more severe hepatic steatosis and higher levels of systemic inflammation, as indicated by elevated CAP and CRP levels, respectively." (PMID 40003697, 2025). "The mean values of mean blood pressure, liver enzymes, fasting plasma glucose, triglyceride, and C-reactive protein levels were highest in the group with elevated CEA levels and hepatic steatosis (group 4)." (PMID 37904789, 2023). "Using a multivariate logistic regression, the DICA score, CRP, total cholesterol, HTA, and hypothyroidism were identified as discriminating factors for the presence of hepatic steatosis." (PMID 35056346, 2021).
Hepatic steatosis (continued). "Accordingly, estimates of liver steatosis (transaminases, HSI) and inflammation (CRP) demonstrated a long-term improvement between baseline and T18." (PMID 34611132, 2021). "The DICA score, CRP, total cholesterol, and presence of HTA and hypothyroidism were identified as key discriminating factors for the presence of hepatic steatosis in patients with colonic diverticulosis." (PMID 35056346, 2021). "With increasing hepassocin levels, the patients had higher rates of fatty liver, an increased waist-to-hip ratio, neutrophil count and monocyte count, and higher levels of uric acid and BUN as well as hs-CRP and FIB-4 index." (PMID 33390768, 2021). "Roma patients with MetS have higher levels of hs-CRP (high sensitivity C-reactive protein) and GGT (gamma-glutamyl transpeptidase), which is a surrogate marker for fatty liver disease." (PMID 32365672, 2020). "Overall, patients who had hepatic steatosis had significant higher BMI, Ci, WC, WHR and WHtR; besides, they also had significant higher fetuin A, chemerin, HOMAR-IR, hs-CRP, T-CHO, TG and lower adiponectin levels." (PMID 22815691, 2012). "First, hepatic steatosis induces chronic low-grade inflammation, characterized by elevated inflammatory cytokines (e.g., IL-6, TNF-α) and C-reactive protein (CRP), which can affect the central nervous system by altering neurotransmitter metabolism and impairing mood regulation." (PMID 41011102, 2025). "A hs-CRP cutoff < 7 mg/L had a reasonable specificity; that is, it allows for correct reporting of approximately 80% of patients without documented liver steatosis or fibrosis at biopsy as true negative." (PMID 37029427, 2023). "Interestingly, a study on rats showed that increased CRP levels can be an early sign of Alcoholic Fatty Liver (AFL), whereas another study concluded that CRP seems to be an accurate marker of alcoholic hepatitis." (PMID 37873776, 2023). "Compared with the first tertile, participants in the third DRR tertile with and without hepatic steatosis seemed to be older, more likely to be female, and non-Hispanic black and to have elevated CRP and low eGFR." (PMID 37447388, 2023). "CRP alone was recognized as a predictor of liver steatosis and fibrosis in MAFLD subjects, but it is a non-specific marker of liver inflammation." (PMID 37630857, 2023). "We performed mediation analyses to assess the mediating effects of C-reactive protein (CRP) and red cell distribution width (RDW) on the relationship between dietary sodium and NAFLD defined by the hepatic steatosis index (HSI) and the fatty liver index (FLI), respectively." (PMID 36109506, 2022). "C-reactive protein and hs-CRP are markers of simple fatty liver and NASH, respectively." (PMID 32425736, 2020). "Importantly, the Adpn/Lep ratio was better correlated with the markers of inflammation CRP, WBC and fibrinogen than VAI as well as with the AST/ALT ratio, a marker of hepatic steatosis." (PMID 30813240, 2019). "The aim of this study was to explore the association among MHO, MUNW, and markers of subclinical CVD burden as assessed by high sensitivity C-reactive protein (CRP) and hepatic steatosis (HS) in individuals without overt CVD." (PMID 25838943, 2015). "Low choline diet led to transcriptional changes in peripheral lymphocytes.Gene signature associated with the presence or absence of organ dysfunction (fatty liver and elevated plasma CRP).SNPs in MTHFD1, CHDH and PEMT influence the diet-induced changes in gene expression profile." (PMID 40821837, 2025). "After the VLCKD, liver steatosis, body weight, waist circumference, FFM, diastolic blood pressure, fasting triglycerides, AST, ALT, γGT, ferritin, uric acid, creatinine, and HDL-cholesterol levels were significantly higher in men, whereas CRP levels were higher in women." (PMID 38794646, 2024).
Hepatic steatosis (continued). "Additionally, in this study, using a multivariate logistic regression, the DICA score, CRP, total cholesterol, and presence of HTA and hypothyroidism were identified as key discriminating factors for the presence of hepatic steatosis in patients with colonic diverticulosis." (PMID 35056346, 2021). "Moreover, C-IMT was significantly higher in those with NAFLD than in those without fatty liver when CRP level was kept constant." (PMID 27226159, 2016). "CRP may be a marker of hepatic steatosis but not of severity of NAFLD in obese patients." (PMID 24252302, 2013). "It is no wonder that hs-CRP is a non-invasive complementary marker of NAFLD, and its high levels are common in this population due to the interplay between fatty liver and cardiometabolic problems." (PMID 35958257, 2022). "Similarly, the mean carotid IMT increased gradually with increasing CRP in both subjects with NAFLD and in those without fatty liver (p < 0.001)." (PMID 27226159, 2016).
bacterial pneumonia (122 papers, 2005 to 2026). Acute infection of the lung parenchyma caused by bacteria (e.g., Streptococcus pneumoniae, Haemophilus influenzae, Chlamydia pneumoniae, Mycoplasma pneumoniae, and Legionella pneumophila). "Although some studies have reported associations between elevated CRP levels and bacterial pneumonia, the proposed thresholds were ≥4 or ≥5 mg/dL." (PMID 41153485, 2025). "CRP is a recognized acute-phase reactant, with previous studies indicating a significant correlation between increased complication risk and severe bacterial pneumonia when CRP levels exceed 40 mg/L." (PMID 41018059, 2025). "In our study, bacterial pneumonia was also associated with higher CRP, PCT, NT-proBNP, creatinine, and urea values, reflecting the greater inflammatory and systemic burden of bacterial infections." (PMID 41307635, 2025). "Elevations in C-reactive protein (CRP) concentrations are associated with bacterial pneumonia and normalization precedes radiographic resolution of disease, making it a more sensitive indicator of disease resolution." (PMID 38891647, 2024). "These associations have led to the use of CRP for discriminating between bacterial and non-bacterial pneumonia." (PMID 37275364, 2023). "C-reactive protein (CRP), which is an acute phase reactant and one of the indicators of acute inflammation, has been linked to bacterial coinfections like bacterial pneumonia." (PMID 35655792, 2022). "The multivariate analysis showed that patients who have bacterial pneumonia and CRP > 130 mg/L were at risk of bad outcome." (PMID 34976074, 2021). "Higher CRP values are more likely to be associated with bacterial pneumonia with a variable cut-off between different studies." (PMID 32637387, 2020). "The Feverkidstool is a clinical prediction model combining clinical characteristics and C-reactive protein (CRP) to predict the risk of bacterial pneumonia and other serious bacterial infections in children." (PMID 32004317, 2020). "CRP levels of ≥40 mg/L are associated with confirmed bacterial pneumonia especially S. pneumoniae and H. influenzae, and negatively associated with RSV pneumonia." (PMID 31422032, 2019). "In this cohort, the PCT level was a sensitive marker (sensitivity 85.5%, negative predictive value (NPV) = 82.2%) and exceeded the diagnostic capabilities of CRP to identify bacterial pneumonia." (PMID 31183362, 2019). "Elevated CRP was positively associated with confirmed bacterial pneumonia and negatively associated with RSV pneumonia in PERCH." (PMID 28575375, 2017). "Our analyses showed that elevated CRP was positively associated with confirmed bacterial pneumonia, especially Spn and Hinf, and negatively associated with RSV pneumonia." (PMID 28575375, 2017). "In another Gambian study, CRP, lipocalin-2 and vWF were associated with pediatric bacterial pneumonia using a composite diagnosis based on radiography, blood culture, and WBC count." (PMID 26366571, 2015). "Total WBC count had the best diagnostic accuracy for predicting bacterial pneumonia, and its diagnostic performances was better than those of serum procalcitonin and C-reactive protein concentrations." (PMID 24824328, 2014). "Increased CRP levels may indicate bacterial pneumonia, especially if associated with a high white blood cell count." (PMID 38541845, 2024). "However, we recommend a low threshold for CRP measurements and risk assessments for bacterial pneumonia in these children, and withholding antibiotics in children with a predicted risk of ≤10%, provided that careful safety-netting and good access to healthcare are in place." (PMID 32004317, 2020). "CRP levels have been shown to correlate with the severity of bacterial infections, helping to distinguish bacterial pneumonia from viral pneumonia and guiding the decision to initiate or withhold antibiotics." (PMID 40693097, 2025).